INS (insulin)
Diseases named in the same sentence as INS in open-access papers (continued):
Sharing a sentence is not in itself a finding about the gene and the disease.
Insulin resistance (continued). "It should be emphasized that the only drug and dosage able to revert the sucrose-induced insulin resistance was the GSNO in a dosage of 100 μmol/kg; however, 50 μmol/kg of GSNO was already modestly but significantly capable of promoting an increase in insulin sensitivity." (PMID 32942712, 2020). "In Insulin resistance situations, the administration of insulin is not effective in the long term; thus, other treatments have been developed instead to enhance the insulin sensitivity, rather than overload the system with insulin." (PMID 33228179, 2020). "Adiponectin, an adipose-derived hormone involved in insulin sensitization and fuel disposal from the blood, is lower in women with PCOS and as a result may contribute to insulin resistance." (PMID 33467251, 2020). "We used fasting glucose and insulin as proxies for insulin resistance, however these are not direct measures of insulin resistance." (PMID 33063664, 2020). "As observed in adults with obesity, our data as well as that of other researchers indicate that elevated insulin or insulin resistance is not uncommon in Hispanics children with obesity." (PMID 33266497, 2020). "There was no insulin resistance in C3H-Chr 11NSY and C3H-Chr 14NSY mice and normal insulin secretion in response to glucose in C3H-Chr 14NSY mice at 3 months of age." (PMID 32703163, 2020). "Unlike Westerners, insulin secretion is not increased in Asians to normalize serum glucose concentrations when insulin resistance is increased." (PMID 31991596, 2020). "Randomised controlled trials (RCTs) ≥6 weeks in duration, reporting ≥1 of the following: fasting blood glucose (FBG), fasting blood insulin (FBI), glycosylated haemoglobin (HbA1c), homeostatic model assessment-insulin resistance (HOMA-IR), or 2-h postprandial glucose (2-h PPG), were deemed eligible." (PMID 32708949, 2020). "In present study, INU intervention significantly improved glucose tolerance and insulin resistance, indicating that INU may improve insulin sensitivity in NAFLD." (PMID 33390939, 2020). "Neither diet condition significantly altered insulin sensitivity indices, but the homeostasis model assessment for insulin resistance was significantly (p = 0.028) higher after the Non-Egg vs. the Egg condition." (PMID 32152513, 2020). "A number of studies have shown that long-term HFD feeding result in dysregulated glucose homeostasis and insulin resistance, and our results confirmed that APS could normalize the fasting blood glucose and insulin levels in HFD-fed mice." (PMID 32587515, 2020). "But, cholesterol treatment per se did not alter mitochondrial function, insulin action and palmitate-induced insulin resistance in vitro." (PMID 32456175, 2020). "In C3H-Chr 14NSY mice, sucrose administration induced glucose intolerance, but not insulin resistance and impaired insulin secretion." (PMID 32703163, 2020). "Patients with T2DM have either insulin resistance (sugar transfer dysregulation into cells) or lack of optimal insulin secretion to sustain natural glucose levels." (PMID 33382706, 2020). "Actually, the condition of insulin resistance represents a significant link among components of MS even if a subject with MS not necessarily is insulin resistant." (PMID 31963572, 2020). "On the whole, the glucose fall from baseline during first 30 minutes of the insulin tolerance test showed that male offspring of fat-1 dams had protection from insulin resistance, whereas female offspring did not." (PMID 32183350, 2020). "Villa-Pérez et.al reported that liver-specific ablation of IDE leads to hepatic insulin resistance and glucose intolerance without affecting insulin clearance in mice." (PMID 32550230, 2020). "Meanwhile, the transduction of the insulin PI3K/AKT signaling pathway is weakened, which may be the major manifestation of insulin resistance, impacting the downstream mediator—glycogen synthase kinase-3β (GSK3β)." (PMID 32982969, 2020).
Insulin resistance (continued). "Recent studies and our previous clinical experience have shown that some patients did not develop adequate hypoglycemia with a single dose of insulin in ITTs, probably due to obesity or insulin resistance." (PMID 32328036, 2020). "We did not actively monitor the patient’s response to insulin dosing and calculate the insulin resistance pattern using the HOMA or the QUICKI methods." (PMID 33198177, 2020). "Recent data show that patients with T2DM have a higher risk of Alzheimer’s disease (AD) than patients without T2DM; altered insulin secretion and insulin resistance seems to be the link between T2DM and AD." (PMID 32023991, 2020). "Its possible regulation by insulin and leptin, two hormones closely involved in the regulation of obesity and insulin resistance, has not been systemically explored." (PMID 31936857, 2020). "In the absence of hyperinsulinemia/insulin resistance, the lower insulin levels exert less potential proatherogenic activities which are counteracted by insulin-stimulated local NO production." (PMID 32819363, 2020). "Furthermore, we examined the effect of BAA6 on insulin resistance using an intraperitoneal glucose tolerance test (GTT) and insulin tolerance test (ITT)." (PMID 32218367, 2020). "Consequently, researchers introduced new indirect methods, which were suitable for clinical settings and researches, including; Homeostatic Model Assessment of Insulin Resistance (HOMA-IR) and Quantitative Insulin Sensitivity Check Index (QUICKI)." (PMID 33680012, 2020). "First, plasma TMAO levels, insulin levels and homeostatic model assessment of insulin resistance (HOMA-IR) values were higher in PCOS patients without HA, especially in the obese subgroup." (PMID 31906930, 2020). "Importantly, 16 weeks of HFHSD led to a decreased insulin-stimulated Ser473-AKT phosphorylation in the heart, reflecting a cardiac insulin resistance." (PMID 33258101, 2020). "The resulting “insulin resistance” is not primarily due to less insulin receptor expression on the cell surface but due to impaired insulin signal transduction as a result of receptor dysfunction." (PMID 32819363, 2020). "In fact, there is little evidence that FA per se triggers defects in insulin signaling and induces insulin resistance." (PMID 32887221, 2020). "Taurine supplementation normalized increased serum insulin concentration and insulin resistance index; however, it did not improve serum CRP concentration in high-fat diet fed rats." (PMID 32172503, 2020). "The level of insulin resistance and glucose effectiveness at basal insulin level (Sg) did not significantly differ in the relatives and healthy controls." (PMID 32685554, 2020). "Clinical data showed negative correlations between sclerostin, insulin, and homeostasis model assessment of insulin resistance (HOMA-IR) in 55 children and adolescents with simple obesity." (PMID 32265831, 2020). "Recent studies have proposed that HOMA-IR measurements of insulin resistance refer mostly to the liver, rather than describing peripheral insulin sensitivity." (PMID 32708970, 2020). "Our recent data also demonstrated that chronic psychological stress impairs glucose intolerance and decreases insulin sensitivity in Zucker diabetic fatty (ZDF) rats, suggesting that chronic psychological stress can contribute to the development of insulin resistance in T2DM." (PMID 32372981, 2020). "TNF-α and IL-6 are known mediators of insulin resistance and hyperandrogenaemia was therefore found to have a negative impact on the insulin-mediated IRS-PI3K-Akt signaling pathway." (PMID 33396555, 2020). "Patients present some degree of hepatic insulin resistance, explaining why approximately half of them do not respond to sulfonylureas, needing early insulin therapy." (PMID 32528556, 2020). "Gestational lipid profiles of the diet treatment group were indicative of a lower insulin resistance profile, when compared to both insulin-treated women and those without GDM." (PMID 32240196, 2020).
Insulin resistance (continued). "In the present study, the insulin levels and insulin resistance index were not measured, but similarity was observed in the results of the study." (PMID 33911828, 2020). "Preconceptionally, HOMA and Matsuda indices differed significantly between the two strains, implying increased insulin resistance (NZO vs. NMRI: 12.34 ± 3.09 vs. 1.98 ± 0.44, p = .0001) and decreased insulin sensitivity of the NZO (NZO vs. NMRI: 1.85 ± 0.25 vs. 10.03 ± 1.84, p = <.0001)." (PMID 32374082, 2020). "T2DM is defined as the condition whereby the cells are not responsive to the insulin (insulin resistance or IR) and unable to initiate the insulin-dependent glucose uptake activity." (PMID 32587790, 2020). "Fasting plasma insulin (FPI), the homeostasis model assessment for insulin resistance (HOMA-IR), C-peptide, and type A1c glycosylated hemoglobin (HbA1c) were all measured at baseline and eight weeks after ingestion of test products in the first (0–8 weeks) and second (12–20 weeks) periods." (PMID 32085495, 2020). "The association between the two DM medication categories (taking insulin only and taking both oral medication and insulin) and higher HbA1c and FBG in this study may be due to exacerbation of insulin resistance by the presence of comorbid HF in T2D." (PMID 32802365, 2020). "Even though at the first stages of T2D natural history, the pancreas increases insulin secretion in response to insulin resistance, it does not mean that β cells are functioning normally." (PMID 32397353, 2020). "IAPP, a pancreatic beta cell peptide, can evoke insulin resistance by antagonising insulin in a non-competitive manner." (PMID 32283762, 2020). "They observed a disruption in CAV1 localization in the plasma membrane of adipocytes, complete abolishment of the insulin-stimulated P-Y14 residues of CAV1, and a decrease in GLUT4 translocation to the plasma membrane suggesting CAV1 relevance in hypoxia-induced insulin resistance." (PMID 32082483, 2020). "Hepatic insulin resistance is one of the earliest pathologies to develop in response to metabolic overload; however, it does not affect all insulin-signaling pathways equally." (PMID 32350271, 2020). "In our study, the diabetic and non-diabetic CHC population showed no insulin resistance with normal serum insulin levels." (PMID 33520544, 2020). "HOMA-IR ≥2.5 was determined to confirm the presence of insulin resistance, where in the current study the thyroid nodules were significantly more prevalent in insulin resistant subjects than the non-insulin resistant ones (22% vs. 2% p=0.01)." (PMID 32874434, 2020). "Insulin is an alternative to measure insulin resistance and the lack of consensus of optimal cutoff makes the comparison among studies difficult." (PMID 32033484, 2020). "As an important regulator of insulin and insulin signaling in drosophila, LNK (mammalian homologue of drosophila LNK is considered as SH2B1) may play a role in the development of insulin resistance." (PMID 32911464, 2020). "Even though the insulin level was higher on 15th day in HFD-STZ diabetic control animals, the blood glucose level was not lowered, and this is due to the insulin resistance associated with type II diabetes." (PMID 32584888, 2020). "In addition, SREBP1 has been demonstrated to participate in palmitate acid-induced insulin resistance via regulating IRS-1 expression and insulin signaling pathway in skeletal muscle." (PMID 33109277, 2020). "Although rats fed a powder diet did not gain body weight, they exhibited increased insulin resistance and glucose intolerance in parallel with increased insulin levels." (PMID 32470042, 2020). "There are also sex differences in pubertal insulin resistance, with cisgender girls being more insulin resistant than boys; while insulin resistance is strongly related to BMI and body fat, these do not entirely account for the sex differences seen." (PMID 31544944, 2020).
Insulin resistance (continued). "We found that VDD zebrafish demonstrated sustained expression of genes comprising the INS signaling pathway suggesting no indication of hepatic insulin resistance." (PMID 32994480, 2020). "Firstly, the method of HOMA was not the golden standard to assess insulin resistance and impaired insulin release." (PMID 32260174, 2020). "A major branch of the insulin signaling pathway, the PI3K/AKT pathway, is downregulated in AD and this change may be a major contributor to insulin resistance." (PMID 33100956, 2020). "T2DM, a chronic systematic metabolic disease, is characterized by pancreatic β cells dysfunction and insulin resistance, which are characterized by that insulin is not sensitive to glucose and subsequently develop hyperglycemia and pancreatic β cells loss." (PMID 32116510, 2020). "In addition, our data also imply that despite higher insulin levels, hyperglycemia is greater in LBMI individuals with T2DM suggesting a phenotype of insulin resistance in these individuals." (PMID 33183277, 2020). "C3H-Chr 11NSY mice under a chow diet showed hyperglycemia, impaired insulin secretion, and insulin resistance without obesity, and C3H-Chr 14NSY mice exhibited hyperglycemia and age-dependent insulin resistance with slight obesity." (PMID 32703163, 2020). "In our previous study 6-8, we found that insulin resistance contributes to multidrug resistance in HCC cells via activation of the ER stress, suggesting that KSR2 may be involved in therapy resistance in insulin resistant HCC." (PMID 32210717, 2020). "The homeostasis model of assessment for insulin resistance (HOMA-IR) was developed to estimate insulin sensitivity in non-diabetic individuals and those with non-insulin-dependent diabetes." (PMID 32664522, 2020). "Importantly, most studies investigating the role of the MAM in brain insulin resistance have focused on the hypothalamus, and how the MAM influences insulin signaling in other brain areas remains to be elucidated." (PMID 33329397, 2020). "Interestingly, despite increased adiposity, BAFF−/− mice exhibited significantly enhanced glucose tolerance and insulin sensitivity compared to their WT controls, indicating that knockout of BAFF resulted in improved insulin resistance in aged mice." (PMID 32698539, 2020). "The results showed that administration of ABM significantly enhanced the expression of the main genes and proteins in the insulin‐resistant pathway and then indicated that ABM had a positive effect on amelioration of insulin resistance through the PI3K/Akt signaling pathways." (PMID 32148819, 2020). "Insulin resistance in T2DM and decreased insulin stimulation can impact metabolism in these tissues, which may affect the contents of the cytokines released by these tissues into the blood." (PMID 32596370, 2020). "These differential effects on glycemia in IUGR and non-IUGR groups were observed without significant effects on baseline insulin and insulin response to glucose (AUC), thereby suggesting greater insulin resistance in the IUGR group." (PMID 33167459, 2020). "Interestingly, CRTC2 knock down reduced hepatic gluconeogenesis and triglyceride and improved insulin sensitivity in animal models of T2DM and insulin resistance." (PMID 32020874, 2020). "The sequential development of tissue-specific insulin resistance and metabolic disruptions, rather than simultaneous whole-body desensitization to insulin, serves as the preferential pathological background for type 2 diabetes." (PMID 33171690, 2020). "Given that the levels of serum insulin or insulin resistance have not been assessed, these indices are recommended to be evaluated in future studies." (PMID 33911828, 2020). "Literature review helped us to point that the increased or decreased levels of the most differential metabolites might improve insulin sensitivity in MHO individuals, while they might contribute to insulin resistance in MUHNO ones." (PMID 32405361, 2020).
Insulin resistance (continued). "We evaluated: fasting plasma glucose (FPG), postprandial plasma glucose (PPG), glycated hemoglobin (HbA1c), fasting plasma insulin (FPI), homeostatic model assessment of insulin resistance (HOMA-IR), lipid profile and high sensitivity C-reactive protein (Hs-CRP)." (PMID 32987917, 2020). "Moreover, neither GlycA nor GlycB were correlated with glucose homeostasis indices, like the Homeostatic Model Assessment of Insulin Resistance (HOMA-IR) and the Quantitative Insulin Sensitivity Check Index (QUICKI)." (PMID 32752190, 2020). "The role of endocrine FGFs and fetuin-A in intralipid mediated insulin resistance or in enhanced insulin sensitive states induced by exercise is not fully understood." (PMID 33101202, 2020). "The principle of the insulin index is how a particular food item stimulated insulin secretion independent of underlying insulin resistance, whereas the EDIH is primarily driven by insulin resistance." (PMID 32854644, 2020). "In addition, insulin-induced AKT activation contributes to the cellular glucose uptake, which is attenuated when insulin resistance occurs." (PMID 32698821, 2020). "In addition, old rats also showed increased serum levels of insulin and HOMA-index, and reduced expression of GCK and GSK3β in the liver, which denotes a state of insulin resistance, another important feature of metabolic aging." (PMID 32503213, 2020). "Multiple dietary fiber has a relatively clear effect on the improvement of insulin resistance in type 2 diabetes, but there is still a lack of evaluation of the efficacy and safety of multiple dietary fibers for insulin levels during pregnancy." (PMID 33019401, 2020). "Given the fact that 11 out of 14 study subjects were 60 years old or older and one subject was on insulin treatment, HOMA-IR might have underestimated the reduction in insulin resistance that occurred at the end of 4th week during 4-week intermittent fasting." (PMID 33110154, 2020). "Using an index of insulin resistance, our data suggest that hepatocyte TGR5 signaling may regulate insulin sensitivity." (PMID 32708970, 2020). "When comparing both groups, fasting insulin levels and HOMA-IR were two-fold higher in OWO than in NW group (p < 0.05 for both), indicating some degree of insulin resistance in children and adolescents with overweight and obesity compared to normal weight patients." (PMID 32290434, 2020). "Secondly, this study did not evaluate the circulating insulin level and homeostatic model assessment for insulin resistance (HOMA-IR)." (PMID 32998691, 2020). "A sensitivity analysis was performed to compare patients with a mean BG of ≤120 mg/dL and those > 120 mg/dL, regardless of treatment group, to assess the response to insulin treatment or insulin resistance." (PMID 31901245, 2020). "To induce insulin resistance-like phenotype, we fed APP/PS1 and C57 WT mice with HFD for 6.5 months and, as expected, HFD treatment resulted in weight gain, liver histopathological changes and insulin resistance for both types of mice." (PMID 33291072, 2020). "Type 2 diabetes progresses, as pancreatic β-cells gradually do not generate sufficient insulin to accommodate persistent insulin resistance." (PMID 32544194, 2020). "We observed an increase in glucose concentrations, a decrease in insulin concentrations and no changes in insulin resistance markers." (PMID 33092301, 2020). "The insulin sensitivity index (ISI) was also affected by treatment (5.66 ± 0.48, 4.62 ± 0.45, for DECAF and CAF, p = 0.0016) and was significantly lower following CAF treatment, indicating insulin resistance due to CAF consumption." (PMID 33339359, 2020). "Interestingly, however, despite increased adiposity, BAFF−/− mice showed improved insulin sensitivity, suggesting that BAFF depletion ameliorates aging-dependent insulin resistance." (PMID 32698539, 2020).